EML4 (EMAP like 4)
Diseases named in the same sentence as EML4 in open-access papers (continued):
Sharing a sentence is not in itself a finding about the gene and the disease.
lung adenocarcinoma (continued). "Moreover, PD-L1 protein expression was significantly increased when EML4-ALK expression was induced in human lung adenocarcinoma cells." (PMID 35984185, 2022). "The EML4-ALK rearrangement gene has high prevalence in selected lung adenocarcinoma and EGFR mutation-negative populations." (PMID 33425389, 2020). "A subset of lung adenocarcinomas is driven by the EML4‐ALK translocation." (PMID 32558295, 2020). "In addition, we targeted ALK in the EML4-ALK fusion oncogene in the H3122 cell line model for human lung adenocarcinoma." (PMID 33255340, 2020). "As an illustration, in the lung adenocarcinoma dataset, we also found a tumor with EML4-ALK fusion." (PMID 30255803, 2018). "Alternatively, detecting the presence of the echinoderm microtubule-associated protein-like 4 (EML4)-anaplastic lymphoma kinase (ALK) fusion gene, termed the ALK-rearrangement, is routinely performed in lung adenocarcinomas and allows the treatment of such patients with anti-ALK targeted therapy." (PMID 28432274, 2017). "The EML4-ALK fusion oncogene is present in 3.7 to 6.8 % of patients with lung adenocarcinomas." (PMID 26964537, 2016). "Therefore, we diagnosed the patient as having EML4-ALK-positive lung adenocarcinoma with a TNM classification of T3N1M1b, Stage IV." (PMID 27872133, 2016). "EML4-ALK gene fusions occur in 2% to 7% of lung adenocarcinomas." (PMID 25527865, 2014). "Although EML4–ALK translocation was first identified from a lung adenocarcinoma specimen surgically resected from a 62-years-old man with a history of smoking, increased evidence suggests that it is much more common in never-smokers based on the studies performed in different countries." (PMID 25407901, 2014). "Although the frequency of EML4-ALK rearrangements is lower in lung SqCC than that in lung adenocarcinomas, their presence may provide additional treatment options in lung SqCC." (PMID 25527865, 2014). "Therefore, a stepwise approach to test for gene mutations in lung adenocarcinoma is suggested: first for KRAS, second for EGFR, and then EML4-ALK translocation." (PMID 23341890, 2013). "Furthermore, to validate the results using clinical specimens, we extracted phosphoproteome data for tumour tissue and normal tissue adjacent to the tumour (NAT) in EML4-ALK–positive patients from Clinical Proteomic Tumor Analysis Consortium (CPTAC) lung adenocarcinoma data." (PMID 35508387, 2022). "In the present study, we report the cases of two synchronous lung adenocarcinomas, composed of two distinct pathological subtypes harboring epidermal growth factor receptor (EGFR) gene mutation and echinoderm microtubule-associated protein-like 4-anaplastic lymphoma kinase (EML4–ALK) rearrangement." (PMID 32727606, 2020). "Moreover, development of personalized medicine of lung adenocarcinoma, the discovery of various genetic alterations that promote cancer growth and survival, such as EGFR mutations and EML4-ALK rearrangements, have revolutionized treatment paradigms for patients." (PMID 28018791, 2016). "This case underscores the critical importance of retesting for resistant mechanisms, such as EML4‐ALK fusion, in patients with EGFR‐mutant lung adenocarcinoma who experience rapid progression on EGFR‐tyrosine kinase inhibitor (TKI) therapy." (PMID 41497773, 2026). "The final diagnosis was stage IV lung adenocarcinoma with a concurrent EGFR exon 19 deletion and EML4‐ALK fusion." (PMID 41497773, 2026). "Examples include BCR::ABL1 in LAMA84, a blast phase chronic myeloid leukaemia (CML-BP) cell line and EML4::ALK in NCI-H2228 (also known as H2228), a lung adenocarcinoma cell line." (PMID 41421967, 2025). "This is the first case presenting a rare coexistence of a novel ALK double fusion, namely, ELMOD3-ALK and EML4-ALK, in a patient with lung adenocarcinoma who demonstrated favorable sensitivity to alectinib." (PMID 40297141, 2025).
lung adenocarcinoma (continued). "In conclusion, we hereby report, for the first time, a case of lung adenocarcinoma harboring a novel ELMOD3-ALK and EML4-ALK double-ALK fusion." (PMID 40297141, 2025). "Herein, we first report a lung adenocarcinoma patient with the coexistence of a novel subfamily 3 of ELMOD (ELMOD3)-ALK, EML4-ALK double fusion that is sensitive to alectinib target therapy." (PMID 40297141, 2025). "This is the first report of one lung adenocarcinoma patient with a novel ELMOD3-ALK, EML4-ALK double-ALK fusion." (PMID 40297141, 2025). "Crucially, comprehensive profiling uncovers co‐occurring drivers (e.g., synchronous EML4‐ALK and TPM3‐ROS1 in bilateral lung adenocarcinomas) or histologic mimics (e.g., TPM3‐ALK+ cutaneous epithelioid vascular tumors masquerading as melanocytic lesions)." (PMID 41275415, 2025). "This fact is particularly relevant in lung adenocarcinoma, since some of the oncodrivers of this histological subtype are HSP90 clients such as EGFR, HER2, MET, BRAF, and the EML4-ALK fusion protein." (PMID 37762133, 2023). "A large proportion (∼5 percent) of lung adenocarcinoma patients as well as breast and colorectal tumors are found in pathological fusion sections of this gene with portions of ALK gene that produces the EML4-ALK transcript." (PMID 33986802, 2021). "EML4–ALK fusion, observed in about 3%–7% of human lung adenocarcinoma, is one of the most important oncogenic drivers in initiating lung tumorigenesis." (PMID 33976114, 2021). "In this report, we identified a rare double ALK fusion, EML4-ALK and CDK15-ALK, in the patient with lung adenocarcinoma." (PMID 33157918, 2020). "Here, we report a case of a 64-year-old Chinese woman who was diagnosed with lung adenocarcinoma (ADC) who concurrently harbored two types of ALK-rearrangements, including an unreported NLRC4-ALK fusion and EML4-ALK fusion." (PMID 32212216, 2020). "Although ALK inhibitors are effective in most patients with EML4-ALK positive NSCLC, the eventual development of acquired resistance remains a major concern in the treatment of EML4-ALK translocated lung adenocarcinomas." (PMID 30658414, 2019). "The initial pathologic diagnosis was lung adenocarcinoma stage IIIa (pT3 pN1 Mx), KRAS wild-type, harboring EGFR exon 19 deletion and EML4-ALK rearrangement." (PMID 28938691, 2017). "Analyses of five driver genes, including EGFR, KRAS, BRAF, HER2 and EML4-ALK, were performed in patients with treatment naïve lung adenocarcinoma." (PMID 25789627, 2015). "Although the oncogenic activity of SFN is weaker than that of EML4-ALK fusion kinase, SFN also appears to have the potential to initiate lung adenocarcinoma." (PMID 26223682, 2015). "Since the fusion of echinoderm microtubule-associated protein like-4 (EML4)−anaplastic lymphoma kinase (ALK) was discovered in non-small cell lung cancer (NSCLC), ALK rearrangements have been reported in 3–8% of lung adenocarcinomas." (PMID 36081848, 2022). "Recent studies have revealed that complex genomic rearrangements generated 74% of known fusion oncogenes in human lung adenocarcinoma of non-smokers, including EML4-ALK, CD74-ROS1, and KIF5B-RET." (PMID 34271921, 2021). "Since EGFR, BRAF, ERBB2, MET and the EML4-ALK translocation product are clients of HSP90, acting as oncodrivers in different clinico-pathological subsets of lung adenocarcinoma, degradation of these oncoproteins through HSP90 inhibition leads to loss of tumor-cell viability." (PMID 31370342, 2019). "Lung adenocarcinoma cell lines from different backgrounds were characterized based on protein expression levels measured for HSP90, other related HSPs and HSP90 client proteins such as EGFR and EML4-ALK." (PMID 31370342, 2019). "Particularly interesting were the results of a study performed by Hong and coworkers based on the screening of a total 1160 Chinese NSCLC patients: 78% lung adenocarcinomas, 54% never-smokers, 33.8% with EGFR mutations and 8.1% with EML4-ALK rearrangements." (PMID 30060526, 2018).
lung adenocarcinoma (continued). "We present the first portrait of clinically actionable alterations in lung adenocarcinoma of Indian origin that includes EGFR, KRAS, EML4-ALK, AKT1, PIK3CA, FGFR4 and ERBB2, similar to that identified in other ethnic groups, and an additional subset of patients with FGFR3 mutations." (PMID 27998968, 2017). "In the Cohort 2 analysis, 29 of 295 patients with EGFR-wild type lung adenocarcinoma (9.8%) were found to have EML4-ALK translocation and none of them harbored other driver gene mutations." (PMID 25789627, 2015). "More specifically, the EML4-ALK fusion gene was found in 23.7% of never-smoker female lung adenocarcinoma patients." (PMID 25760072, 2015). "Because EML4-ALK fusion is not as frequent as EGFR gene mutation, it would be important to efficiently and accurately identify those lung adenocarcinomas that harbor ALK rearrangements in clinical practice to guide the appropriate therapy 9,10." (PMID 24403104, 2014). "As EML4-ALK fusion is not as frequent as EGFR gene mutation, it would be important to efficiently and accurately identify those lung adenocarcinomas that harbor ALK rearrangements in clinical practice to guide the appropriate therapy." (PMID 24403104, 2014). "In addition to the EML4-ALK fusion, not only other fusion partner for ALK gene, but also novel kinase gene fusions have been discovered in a subset of lung adenocarcinoma." (PMID 23617234, 2013). "In our previous study, approximately 90% of lung adenocarcinomas from never smokers harbor known oncogenic mutations in just 4 genes of EGFR, KRAS, HER2, EML4-ALK." (PMID 22140546, 2011). "EML4-ALK is most often detected in never smokers with lung adenocarcinoma and has unique pathologic features." (PMID 21645460, 2011). "Moreover, the co-existence of EGFR gene mutations, ALK gene fusions, and ROS1 gene rearrangements has been reported in a few lung adenocarcinoma cases, but the co-alteration of ROS1, EGFR, and EML4-ALK in MPA remains unclear." (PMID 32677962, 2020). "Compared with non-adenocarcinomas, the overall OR of EML4-ALK in lung adenocarcinomas was 2.53." (PMID 25360721, 2014). "Similarly, EML4-ALK fusion gene was not a significant prognostic factor based on the analysis of 720 resected lung adenocarcinomas." (PMID 27234388, 2013). "Histological conversion has also been observed in EML4-ALK positive patients and in patients with lung adenocarcinoma and no targetable molecular alterations." (PMID 33922215, 2021). "The KIF5B-RET rearrangement is detected with the frequency of 1 ~ 2 % in ‘triple marker’-negative lung adenocarcinomas, i.e., EGFR, KRAS and EML4-ALK wild type." (PMID 26268359, 2015).
anaplastic large cell lymphoma (24 papers, 2012 to 2025). Anaplastic large cell lymphoma (ALCL) is a rare and aggressive peripheral T-cell non-Hodgkin lymphoma, belonging to the group of CD30-positive lymphoproliferative disorders, which affects lymph nodes and extranodal sites. "While anaplastic lymphoma kinase (ALK) gene fusion was seen in large-cell lymphomas, its fusion with the promoter gene, echinoderm microtubule-associated protein-like 4 (EML4), was first discovered in 2007 in NSCLC as an oncogenic driver alteration." (PMID 39941723, 2025). "Anaplastic lymphoma kinase (ALK) is a receptor tyrosine kinase, initially discovered in anaplastic large cell lymphoma, but chromosomal rearrangements resulting in a fusion gene, most commonly with echinoderm microtubule-associated protein-like 4 (EML4), occur in 3-7% of NSCLC." (PMID 36910642, 2023). "ALK rearrangements were initially identified in large-cell lymphomas, but the discovery of the EML4-ALK fusion in NSCLC in 2007 established ALK as a key oncogenic driver in this disease." (PMID 41373672, 2025). "ALK’s most common fusion partners are the NPM1 gene in anaplastic large cell lymphoma and EML4 in epithelial tumors." (PMID 31007851, 2019). "Nearly 30 different ALK fusion protein partners have been described, with echinoderm microtubule-associated protein-like 4 (EML4) and nucleophosmin (NPM) being the most prevalent in NSCLC and anaplastic large cell lymphoma (ALCL) occurring in 3% to 5% and more than 50%, respectively." (PMID 31731495, 2019). "However, the EML4-ALK chimeric protein activates AKT and ERK pathways in EGFR mutation–positive NSCLC, while NPM-ALK fusion promotes ERK and STAT3 pathways in anaplastic large cell lymphoma." (PMID 31007851, 2019). "Moreover, treatment with the anti-VEGF-A antibody bevacizumab strongly impaired Anaplastic Large Cell Lymphoma (containing EML4-ALK rearrangement) growth in mouse xenografts." (PMID 29318404, 2018). "Crizotinib (PF-02341066) is approved for the treatment of non-small cell lung cancer (NSCLC) and anaplastic large cell lymphoma (ALCL), which harbor the fusion oncogenes EML4-ALK and NPM-ALK, respectively." (PMID 27732954, 2016). "For example, presence of the fusion protein EML4-ALK has been found to define histologically-distinct subsets of lung cancer, and ALK-positive anaplastic large cell lymphomas (ALCL) appear to have a better prognosis than ALK-negative ALCLs." (PMID 22347506, 2012). "Many translocations have been found with this ALK gene, including EML4:ALK which is responsible for approximately 3-5% of non-small-cell lung cancer(NSCLC), RANBP2:ALK, TPM4:ALK in inflammatory myofibroblastic tumor, NPM1:ALK, ATIC:ALK, TFG:ALK in anaplastic large cell lymphoma, and so on." (PMID 24564548, 2013).
neuroblastoma (13 papers, 2013 to 2023). Neuroblastoma (NB) is the most common solid, extracranial childhood tumor. "In contrast to the oncogenic ALK-F1174S mutation that has been reported to be activating in the context of full-length ALK in neuroblastoma, EML4-ALK (F1174S) variant 1 exhibits impaired kinase activity leading to loss of oncogenicity." (PMID 38264745, 2023). "In addition, the IC50 values for the four ALK inhibitors in the F1174L neuroblastoma cell lines were 10 to 100-fold higher than the IC50 values in Ba/F3 cells expressing EML4-ALK F1174L mutant." (PMID 28425916, 2017). "We also included analysis of the ALK-G1269A mutant, which has so far not been observed as a neuroblastoma mutation but has been described as a more resistant mutation arising in EML4-ALK from NSCLC patients treated with crizotinib." (PMID 27049722, 2016). "Tumour growth was stunted by trametinib in N-Ras mutant (Q61K) neuroblastoma and EML4-ALK fusion-positive NSCLC xenografts, but not in the ALK-addicted neuroblastoma tumours." (PMID 37414143, 2023). "Although it has only been described in EML4-ALK fusions, we have included ALKG1269A here in the context of full-length ALK, motivated by the potential future relevance for neuroblastoma patients that may be treated with ALK inhibitors." (PMID 27483357, 2016). "One such inhibitor, the first 3rd generation ALK (and ROS1) inhibitor PF-06463922 (lorlatinib), exhibits increased potency against F1174L, 1151Tins, I1171T and G1269A in preclinical EML4-ALK models, with impressive anti-tumour activity observed in xenograft neuroblastoma models harboring F1174L." (PMID 27009859, 2016).
breast carcinoma (11 papers, 2008 to 2024). "Collectively, these observations suggest that EML4-ALK abnormalities are likely relatively rare in breast cancers in general, with ALK gene expression and activation of the ALK signaling pathway more common in TNBC." (PMID 24102046, 2013). "There is evidence that IBC cases has a higher prevalence of OC use than other breast cancer cases, which suggests that EML4 may interact with the effect of OC use through inflammatory-related pathways." (PMID 36303815, 2022). "They detected EML4-ALK fusion in 5 of 209 breast carcinomas (2.4%)." (PMID 24156086, 2013). "Although EML4-ALK gene rearrangement has been studied in solid tumors such as NSCLC, few studies have investigated their role in breast cancers." (PMID 24156086, 2013). "The EML4-ALK translocation found in 4% of NSCLC, and HER2 over-expression in breast cancer are predictors of poor prognosis in lung and breast cancer, respectively, as well as effective targets for therapy." (PMID 23577104, 2013). "Their study did not detect any EML4-ALK rearrangements in 90 breast cancer cases included in the study." (PMID 26312204, 2015). "Our data suggest that the EML4–ALK fusion transcript is not present in gastrointestinal or breast cancers and is specific to NSCLC." (PMID 18414414, 2008). "However, the genomic types of the breast cancers that demonstrated EML4-ALK fusion were not reported, nor is it known whether any of the 5 tumors that had the EML4-ALK fusion were associated with clinicopathologic features characteristic of IBC." (PMID 24156086, 2013).
prostate carcinoma (11 papers, 2013 to 2024). A carcinoma that arises from epithelial cells of the prostate gland. "The identification of recurrent gene fusions in common epithelial cancers—for example, TMPRSS2/ERG in prostate cancer and EML4/ALK in nonsmall cell lung carcinomas—has raised the question of whether fusion genes are pathogenetically important also in ovarian carcinomas." (PMID 24504521, 2014). "Fusion transcripts have been found in various cancers, including EML4-ALK in lung, ETV6-NTRK3 in breast, and translocation of genes in the ETS family in prostate cancer." (PMID 27461012, 2016). "EML4-ALK fusion gene and ETS fusion genes exist in NSCLC and prostate cancer, respectively." (PMID 23688269, 2013).
melanoma (10 papers, 2012 to 2023). A malignant, usually aggressive tumor composed of atypical, neoplastic melanocytes. "The rapid transition from scientific findings to clinical application is exemplified by both the finding of BRAF mutations in melanoma in 2002 and FDA approval of vemurafenib for this indication in 2011 and that of the initial finding of EML4-ALK in 2007 and FDA approval of crizotinib in 2011." (PMID 25562798, 2012). "Analogously to METi and EGFRi, the EML4-ALK translocation-based cellular model H3211 was exposed to the ALK inhibitor crizotinib (ALKi) and the BRAF V600E-addicted melanoma cell line G361 to the BRAF inhibitor (BRAFi) vemurafenib." (PMID 36494469, 2022).